SOX10 (SRY-box transcription factor 10)
Diseases named in the same sentence as SOX10 in open-access papers (continued):
Sharing a sentence is not in itself a finding about the gene and the disease.
melanoma (continued). "Melanoma markers such as SOX10, HMB-45, Melan-A, and S100 help distinguish metastatic melanoma from primary colonic malignancies." (PMID 40236344, 2025). "SOX10 promotes the proliferation and growth of melanoma, activating specific targets such as MIT, long non-coding RNA (Inc RNA), SAMMSON, and FOXD3." (PMID 40872623, 2025). "SOX10 is particularly important in melanoma due to its regulatory influence on the MITF pathway, with evidence of direct cross-activation between SOX10 and MITF." (PMID 41155720, 2025). "The TF SOX10 can induce stemness characteristics in melanoma cells and sustain their proliferative and tumorigenic capabilities." (PMID 40458894, 2025). "Here, we propose and apply network biology methods to study melanoma, offering quantitative insights into the role of SOX10 and its targeting microRNAs (miRNAs) on tumor plasticity." (PMID 40458894, 2025). "In this case, melanoma (tumor) cells can be distinguished by SOX10, S100B, and CD63 protein abundance." (PMID 41333415, 2025). "We employed a multiparameter ploidy sorting approach to isolate tumor populations based on DNA ploidy and melanoma biomarkers (SOX10 or S100), enabling us to investigate clonal evolution with high resolution." (PMID 40004220, 2025). "In routine melanoma diagnostics, SOX10 and S100 are commonly used biomarkers for melanoma via immunohistochemistry." (PMID 40004220, 2025). "We selected TEAD1 and TEAD4 for analysis because they are the predominantly expressed TEAD paralogs in many cancer cell lines, including NCI-H226 and MSTO-211H58 and in SOX10 KO melanoma cells." (PMID 41193428, 2025). "Other melanoma-specific markers such as human melanoma black 45 (HMB45), tyrosinase, MART-1/Melan-A, melanocyte-inducing transcription factor (MITF), and sex-determining region Y-box 10 (SOX10), aid in melanoma diagnosis." (PMID 40177537, 2025). "This study discovered that SOX10 suppresses the infiltration of most immune cells in melanoma, with the exception of NK cells." (PMID 40342816, 2025). "In our bio-printed structures, we evaluated the expression of specific immunological markers CK19, specific to pancreatic cancer and SOX10, a specific marker for MeWo cells from malignant melanoma." (PMID 39329875, 2024). "Previous studies have reported that the transcription factor SOX10 drives the dynamic transition of melanoma cells from a melanocytic state to a mesenchymal state." (PMID 39704704, 2024). "The p300 KAT inhibitor A-485 blocks SOX10-dependent proliferation and SOX10-independent invasion in hard-to-treat melanoma cells." (PMID 38994683, 2024). "Endoscopy revealed a polypoid esophageal lesion, confirmed as melanoma via biopsy with positive immunohistochemical staining for Melan-A and SOX-10." (PMID 39712693, 2024). "Sometimes, SOX-10 (SRY-box transcription factor 10) positivity can mislead to malignant melanoma, as in our case, which is why a broad panel of immunohistochemical markers is critical for the definitive diagnosis." (PMID 38476800, 2024). "In this context, the diagnosis of metastatic and recurrent melanoma was established due to the retained expression of SOX10." (PMID 39001214, 2024). "Sox10 is also diffusely positive in most melanomas but is positive in approximately 10% of breast cancers, particularly basal-like carcinomas." (PMID 38910784, 2024). "We have previously reported that genetic knockdown (KD) of the transcriptional coactivator p300 in melanoma cells results in significantly lower expression of SOX10 and MITF proteins." (PMID 38994683, 2024). "In agreement with our findings in human melanoma, we found that aldh1a3 was the most enriched ALDH family isoform in the ALDHHigh cells, together with high tfap2b, sox2, and sox10, while melanoma cells with ALDHLow activity expressed irf1b." (PMID 38963759, 2024).
melanoma (continued). "A search of the CDM further confirmed that p300 drives proliferation in a SOX10-dependent manner, as melanoma cells with high SOX10 expression are more dependent on p300 than those with low SOX10 expression." (PMID 38994683, 2024). "Several proteins are commonly used as markers for melanoma in immunohistochemistry testing: S-100 protein, SOX-10, HMB- 45, PRAME, and MART-1." (PMID 38748192, 2024). "Adequate conjunctival biopsies were stained with hematoxylin and eosin, Melan-A, SOX10, and PReferentially expressed Antigen in Melanoma." (PMID 37924948, 2024). "We then mimicked the melanoma cell states identified by the Visium sequencing using mIF antibodies for SOX10, MITF, B2M and NGFR." (PMID 38594286, 2024). "discovered, through immunohistochemistry, a 100% positive rate of SOX10 expression in schwannomas and a 97% positive rate in melanomas." (PMID 39158355, 2024). "SOX10 is an essential transcription factor in neural crest cells, and is highly expressed in melanoma, contributing to its tumorous behavior." (PMID 39237877, 2024). "According to CRISPR (DepMap Public 23Q2 + Score, Chronos), SOX10 is classified as an essential gene in melanoma (gene score effect less than −1)." (PMID 39237877, 2024). "After single-cell segmentation and quality control, we identified 2,511 melanoma precursor cells positive for melanocytic lineage marker SOX10." (PMID 39091741, 2024). "Real-time PCR analysis showed a dramatic downregulation in the expression level of the SOX10 gene in both resistant melanoma cell lines versus control lines." (PMID 39175042, 2024). "An initial panel of markers should be done to identify the lineage of tumor: carcinoma (cytokeratin AE1/3, OSCAR, CAM5.2), lymphoma (CD20, CD3), melanoma (S-100 protein, SOX10), and sarcoma (desmin, smooth muscle actin, MDM2, ERG)." (PMID 39634259, 2024). "A major challenge has been developing therapeutic strategies targeting SOX10’s role in melanoma proliferation while preventing a concomitant increase in tumor cell invasion." (PMID 38994683, 2024). "Immunohistochemistry is crucial for the definitive diagnosis of melanoma, with markers such as Melan-A, SOX-10, HMB-45, and S-100 used to identify the tumor type." (PMID 39712693, 2024). "In acute myeloid leukemia, FTO was shown to control stem cell differentiation through the ASB2/RARA axis, and FTO was revealed to affect immunotherapy by regulating intracellular factors (PD-1, CXCR4, and SOX10) in melanoma." (PMID 38384328, 2024). "After an eight-week period, the melanoma cells expressing SOX10 consistently led to the development of substantial in vivo tumors (11 out of 14)." (PMID 39611156, 2024). "Given the proximity of the EP300 and SOX10 loci and their significant roles in melanoma development and progression, we sought to explore a functional connection between these two genes in melanoma." (PMID 38994683, 2024). "A cohort of primary melanoma samples from 14 patients were examined using cyclic immunofluorescence (CyCIF) imaging and antibodies against SOX10 (melanocytes), CK14 and panCK (epidermal keratinocytes), PRAME, TET2 and 5-hmC." (PMID 39091741, 2024). "These over-expressed proteins shifted YUMM2.1 cells toward a mesenchymal melanoma transcriptional state related to the switch between SOX10 and SOX9 expression observed in human melanomas." (PMID 38245503, 2024). "The researchers conducted subcutaneous injections of melanoma cells with normal SOX10 expression and melanoma cells with SOX10 silenced by shRNA in immunodeficient NOD/SCID or nude mice." (PMID 39611156, 2024). "Lastly, a recent study reported positive regulation of PD-L1 by SOX10, resulting in impaired T cell recognition of A375 melanoma cells." (PMID 39736644, 2024). "SOX10 is a neural crest lineage-specific transcription factor that regulates melanoma development, rapid tumor growth, and tumor immunogenicity." (PMID 38994683, 2024).
melanoma (continued). "We further show that p300 KAT activity mediates SOX10 protein stability and that the p300 inhibitor A-485 downregulates SOX10 protein levels in melanoma cells via proteasome-mediated degradation." (PMID 38994683, 2024). "All the PDX tumors exhibited confirmatory markers of melanoma, such as SOX10, MELAN-A (MART1), HMB45, or S100B." (PMID 39312285, 2024). "Further analysis reveals that at the injection site (within the white dashed lines), SOX10‐positive melanoma cells successfully express EGR3." (PMID 38973154, 2024). "Because both EP300 and SOX10 have been shown to promote melanoma cell growth and co-bind on chromatin, it is possible that their co-amplification synergistically promotes melanoma cellular growth." (PMID 38994683, 2024). "In current practice, melanomas are diagnosed with the most sensitive markers SOX-10 and S100, and at least one of the more specific markers such as MART-1 or Melan A, HMB45, and tyrosinase." (PMID 39258061, 2024). "Correlating with slower tumor growth rates of YUMM2.1-dHLH tumors, the percentage of Ki67+ melanoma cells (Sox9+ or Sox10+ cells) were lower in YUMM2.1-dHLH compared to YUMM2.1-WT tumors." (PMID 38245503, 2024). "Feature heatmaps of melanoma (SOX10) and LEC (PROX1) markers showed that melanoma cells localized to 2 clusters (Melanoma I and II), and the remaining clusters (LEC I–VII) consisted of LECs and LECs*." (PMID 37971882, 2024). "The involvement of SOX10 in melanoma immunogenicity has been studied extensively, showing that its loss sensitizes tumor cells to T-cell mediated killing, and it is a direct transcription factor for immune molecules such as CEACAM1 and IRF4." (PMID 39237877, 2024). "More interestingly, neural crest stem cell markers (including NES and SOX10) that are more relevant to melanoma biology were also greatly changed." (PMID 39728923, 2024). "SOX10 is a thread-specific transcription factor that promotes the development of neural crest cells and contributes to the growth of melanoma cells." (PMID 39611156, 2024). "Nuclear transcription factor SOX10 plays an important role in melanocytic cell differentiation and has been shown to be a sensitive marker of spindle and desmoplastic melanoma." (PMID 39329865, 2024). "Mining of a SOX10 KD dataset identified MITF, SCD, and MYC as being downstream SOX10 effector genes in this melanoma phenotype." (PMID 38994683, 2024). "To confirm these results, we also used immunohistochemistry to co-stain for SOX10 (a melanoma marker) and CXCR2." (PMID 37270599, 2023). "Other markers including cytokeratin AE1/3 (for epithelial cell origin), CD31 (for endothelial cells), SOX10 (for melanoma), IBa-1 (for histiocytic sarcoma), and CD117 (for mast cell tumor) were all negative." (PMID 36875999, 2023). "Histopathological analysis of viable tumor tissue (H&E staining and Ki67 IHC staining) revealed increased PD-L1 expression in SOX10-positive melanoma cells located exclusively near CD3+ T cell-enriched melanoma regions, close to necrotic tumor areas." (PMID 38102680, 2023). "The IHC markers S-100, SOX10, and Melan-A contributed to better evaluation of the melanoma invasion, especially in thin melanomas, but their impact on staging and consecutive treatment remains to be confirmed by future studies." (PMID 36980327, 2023). "As melanomas approach their proliferative limits or the threshold for potential invasion, SOX10 has been observed to become downregulated within the tumor cells." (PMID 38132479, 2023). "The expression of SOX10 in melanoma has been conducted due to its significance in both diagnostic and therapeutic applications." (PMID 38132479, 2023). "PM shares the immunophenotype of melanomas, including expression of SOX-10, S100, Melan-A, and HMB-45." (PMID 37898793, 2023).
melanoma (continued). "The spotlight on SOX10 intensifies in melanoma, where its impact on crucial factors like MITF and cell migration shapes tumor progression and treatment responses." (PMID 38132479, 2023). "Histopathology confirmed the diagnosis of melanoma based on the melanocytic markers, SOX-10 and Melan-A; dedifferentiation was demonstrated within the orbital tumor." (PMID 37559849, 2023). "Melanoma cells and CTLs were identified by Sox10 (a nuclear marker of melanocytic lineage, orange) and CD8 (a CTL marker, purple) expression respectively and cell lysosomal content was identified by CD107a staining (black)." (PMID 37932311, 2023). "Here, we aimed to explore the complex mechanisms behind the MITF/SOX10‐controlled RTK‐induced drug resistance in melanoma." (PMID 36251678, 2023). "For spindle cell desmoplastic melanomas, S100 and SOX10 continues to play a key role in their diagnosis as lower sensitivity ranging from 20 to 35% was observed." (PMID 38076247, 2023). "Third, ASTER also outperformed other methods on Melanoma (a dataset of cells in time series after knockdown of SOX10 in two short-term patient cultures)." (PMID 36610708, 2023). "A reduction in SOX10 expression resulted in reduced melanoma formation, and the knockout of the SOX10 gene led to the elimination of new tumor formation." (PMID 38132479, 2023). "SOX10 (Sry-related HMg-Box Gene 10) is a transcription factor that facilitates neural crest cell development and is also involved in melanoma cell growth through the regulation of immune checkpoint protein expression." (PMID 37687080, 2023). "SOX10 expression has been identified in various cancer types, including breast tumors, glioma, glioblastoma, salivary adenoid cystic tumors, melanoma, and hepatocellular carcinoma." (PMID 38132479, 2023). "SOX10 exhibited higher specificity (96%) compared to Melan-A (17%) in evaluating epidermal malnocytes and consequently in avoiding overdiagnosis of melanoma in situ in sun-damaged skin." (PMID 36980327, 2023). "Studies on SOX10 have extended beyond its role in proliferation with investigations into its involvement in the migration of melanoma cells." (PMID 38132479, 2023). "Immunohistochemical staining mainly detects S-100 protein, anti-melanoma specific antibody 45 protein, melanoma antigen protein recognized by T cell 1 and SRY-box transcription factor 10 protein." (PMID 38065883, 2023). "Eleven clusters were annotated as tumor cells because they expressed high levels of melanoma-associated marker genes (MLANA, MITF, PRAME and SOX10)." (PMID 38065972, 2023). "We have previously shown that the transcription factor SOX10, a major marker of primary melanomas and the melanocytic state, reduces the cancer stem cell properties of melanoma cells." (PMID 38201278, 2023). "While differentiated melanoma cells exhibit high levels of MITF and SOX10, dedifferentiated melanoma cells show low expression of MITF and high expression of mesenchymal markers." (PMID 37370757, 2023). "FABP8 expression was found to be upregulated in a SOX10-dependent manner in melanoma cells and to increase melanoma cell invasion." (PMID 37207357, 2023). "Another potential target to increase melanoma tumor immunogenicity is the transcriptional activator SOX10, which also regulates MITF." (PMID 37626741, 2023). "SOX10 plays an important role in neural crest development and inhibits melanoma cell immunogenicity by inducing the expression of interferon regulatory factor 4 (IRF4), a negative regulator of interferon regulatory factor 1 (IRF1) transcription." (PMID 37626741, 2023). "Up-regulation of SOX10 is believed to, at least in part, contribute to the re-emergence of the neural crest features observed during melanoma initiation and progression." (PMID 38030698, 2023). "In studies focusing on childhood melanoma, almost all congenital melanomas were found to be SOX10 positive." (PMID 38132479, 2023).
melanoma (continued). "PITX1 binds to the promoter region of SOX9, promoting its transcription and thus suppressing the growth and proliferation of melanoma by inhibiting SOX10 and SAMMSON." (PMID 37841446, 2023). "Sox10 is highly expressed in a variety of tumors and plays important roles in tumor initiation, maintenance, and progression to advanced stages of melanoma." (PMID 37108281, 2023). "Studies supporting SOX10 as a more sensitive marker for melanoma, compared to MITF, the previous standard marker for neoplastic testing within this sector, further highlight its diagnostic potential." (PMID 38132479, 2023). "By recapitulating the embryonic microenvironment and preserving key intrinsic molecular features, the AVI‐PDXTM enables melanoma cells to translate their different SOX10‐MITF levels into distinct migratory/invasive behaviors hence modeling ITH." (PMID 36692026, 2023). "The researchers noted that curcumin-enhanced miR-222-3p expression negatively regulated SOX-10 mRNA and ultimately inactivated the Notch pathway, thus limiting melanoma cell proliferation, migration, and invasion." (PMID 36829966, 2023). "Single-cell mRNA sequencing was used to confirm three distinct melanoma cell states in patient-derived cultures—melanocytic lineage behavior, or neural crest-like properties were stratified by expression of SOX10." (PMID 36675114, 2023). "In melanoma, knockdown of FTO promotes YTHDF2-mediated PD-1, CXCR4, and SOX10 mRNA decay, sensitizing melanoma cells to interferon-gamma and anti-PD-1 therapy." (PMID 36859310, 2023). "Here, we show that SOX10 is heterogeneously expressed in melanomas independently of treatment status." (PMID 35296667, 2022). "To further explore the differences observed between in vitro and in vivo findings, we used CRISPR/Cas9 to deplete SOX10 in an MITF-methylated melanoma cell background." (PMID 36040798, 2022). "All cases in this study were IHC stained for melanoma markers (SOX10, S100, Melan-A, and HMB45) and all were positive for primary cutaneous melanoma, uveal melanoma, and conjunctival melanoma." (PMID 36289768, 2022). "The 3 SOX10– melanoma cell lines showed increased migratory potential as compared with the SOX10+ melanoma cell lines (P = 0.000002)." (PMID 36040798, 2022). "After 48 hours of cell growth in ultra-low-attachment plates, we did not observe any significant difference in cell viability between the SOX10+ and SOX10– melanoma cell lines." (PMID 36040798, 2022). "Considering our patient’s history, we performed IHC for marker SOX10, one of the most specific markers for melanoma." (PMID 36289768, 2022). "Although both melanoma and nevi stain positive for S100 and SOX10, markers such as Melan-A, HMB45, and Ki-67 can help differentiate them." (PMID 36289768, 2022). "Together, these data show that SOX10 is heterogeneously expressed in melanoma and SOX10-low populations are present in treatment-naïve samples." (PMID 35296667, 2022). "This included the interferon regulatory factor 4 (IRF4), a transcription factor known to be induced by SOX10 that acts as a negative regulator of IRF1 to repress melanoma immunogenicity." (PMID 36434616, 2022). "We identified that curcumin had a repress effect on SOX10 expression to impede the proliferation, migration, and invasion ability via a dose-dependent manner in melanoma cells." (PMID 35585935, 2022). "Two crucial transcription factors, microphthalmia-associated transcription factor (MITF) and SRY-box transcription factor 10 (SOX10), important in melanoma development and progression, have been implicated in this process." (PMID 36040798, 2022). "SOX10, another well-known melanoma marker is an indispensable protein for melanoma initiation and maintenance, which was used as a marker for metastatic melanoma." (PMID 36232952, 2022).